VDAC3 (voltage dependent anion channel 3)
Description:
Non-selective voltage-gated ion channel that mediates the transport of anions and cations through the mitochondrion outer membrane and plasma membrane. Forms a high-conducting channel with a stable open state and a voltage-induced closure with a mild preference for anions over cations. Involved in male fertility and sperm mitochondrial sheath formation (By similarity).
Synonyms: VDAC-3; HD-VDAC3
Tractability: Antibody: UniProt predicts a signal peptide or a membrane-spanning region. PROTAC: UniProt records ubiquitination sites on it; ubiquitination databases record sites on it; its protein half-life has been measured.
Gene: Protein-coding gene on chromosome 8 (42,391,624 to 42,405,937, forward strand). Ensembl gene ENSG00000078668.
Subcellular location: Mitochondrion outer membrane; Membrane
Subcellular location (Human Protein Atlas): Mitochondria
Pathways (Reactome):
Autophagy: PINK1-PRKN Mediated Mitophagy
Metabolism of proteins: Ub-specific processing proteases
Transport of small molecules: Mitochondrial calcium ion transport
Gene Ontology:
Molecular function: protein binding; voltage-gated monoatomic ion channel activity; voltage-gated monoatomic anion channel activity
Biological process: adenine transport; sperm mitochondrial sheath assembly; spermatogenesis; monoatomic anion transmembrane transport; transmembrane transport
Cellular component: extracellular exosome; membrane; mitochondrion; nucleus; mitochondrial outer membrane
Genetic constraint (gnomAD): Loss-of-function variants: 7 observed, 31.17 expected, observed/expected ratio (o/e) 0.22, 90% interval 0.13 to 0.42. The upper end of that interval is the gene's LOEUF score, 0.42, which puts it in group 1 of 6, group 1 being the genes least tolerant of losing a copy. Missense variants: 242 observed, 329.25 expected, observed/expected ratio (o/e) 0.74, 90% interval 0.66 to 0.82. Synonymous variants: 94 observed, 120.43 expected, observed/expected ratio (o/e) 0.78, 90% interval 0.66 to 0.93.
Homologues: Orthologues: chimpanzee VDAC3 (100% identical), dog VDAC3 (99% identical), guinea pig VDAC3 (98% identical), mouse Vdac3 (98% identical), rabbit VDAC3 (98% identical), macaque VDAC3 (96% identical), rat Vdac3 (96% identical), tropical clawed frog vdac3 (78% identical), zebrafish vdac3 (74% identical), zebrafish zgc:56235 (72% identical), Drosophila melanogaster porin (58% identical), Drosophila melanogaster Porin2 (38% identical), and 2 more. Paralogues in human: VDAC2 (73% identical), VDAC1 (67% identical).
Diseases named in the same sentence as VDAC3 in open-access papers:
VDAC3 is named in the same sentence as 41 diseases in open-access papers, as found by Europe PMC text mining. Sharing a sentence is not in itself a finding about the gene and the disease. The quoted sentences say what the papers report.
gastric cancer (7 papers, 2019 to 2025). A primary or metastatic malignant neoplasm involving the stomach. "The lncRNA BDNF-AS/WDR5/FBXW7 axis modulates ferroptosis in gastric cancer by impacting the ubiquitination of voltage-dependent anion channel 3 (VDAC3), thereby mediating peritoneal metastasis of gastric cancer." (PMID 39827195, 2025). "LncRNA BDNF-AS induces ferroptosis in peritoneal metastasis of gastric cancer through modulation of VDAC3 ubiquitination." (PMID 40303288, 2025). "The BDNF-AS/WD repeat domain 5 (WDR5)/F-box and WD repeat domain-containing 7 (FBXW7) axis regulates ferroptosis in gastric cancer cells by affecting the ubiquitination of voltage-dependent anion channel 3 (VDAC3)." (PMID 38481525, 2024). "As a result, they clarified that IMMT and VDAC3 mRNA levels have the best prognostic value for patients with gastric cancer." (PMID 31583841, 2019).
Infertility (7 papers, 2019 to 2025). "•GK2 seems to interact with Kastor and Polluks, two sperm-specific polypeptides that are directly connected with VDAC proteins.•VDAC3-deficient mice show reduced sperm motility and consequent infertility." (PMID 41008556, 2025). "The ultrastructure and formation of the mitochondrial sheath have been described in previous studies, and knockout of several genes (e.g., ARMC12, SPATA33, and VDAC3) is known to cause abnormal mitochondrial sheath formation and subsequent infertility." (PMID 38443933, 2024). "Deletion of VDAC3 causes infertility, while defective VDAC3 causes a significant reduction in sperm motility." (PMID 36246397, 2022). "A significant degree of growth retardation characterizes VDAC1/3 −/− mice; and VDAC3 −/− deficient male mice show the peculiarity of infertile, with a disassembled sperm tail, the flagellum essential for sperm motility." (PMID 33036380, 2020). "While VDAC1 is mainly located in cells of reproductive organs necessary to support the development of gametes, VDAC2 and VDAC3 are expressed in a specific portion of sperm and oocyte, and genetic variants or the aberrant regulation of these genes are correlated with infertility." (PMID 33036380, 2020). "Several CDK2-bound genes have also been implicated in other aspects of germ cell development, including Palb2, Pds5b, Safb1, and Herc4, or have been investigated as potential markers of infertility in human populations: Mtrr and Vdac3." (PMID 31350280, 2019). "Furthermore, it has been reported that genetic variation of the VDAC3 gene is related to diminished semen quality in males with definite idiopathic infertility, and male mice lacking VDAC3 show markedly reduced sperm motility and are infertile." (PMID 39456223, 2024).
male infertility (7 papers, 2016 to 2025). The inability of the male to effect fertilization of an ovum after a specified period of unprotected intercourse. "Damage in the integrity of microtubule doublet structure has been shown to be associated with sperm motility defects and male infertility, as seen for the deletion of Ccdc176, Tmem232, Cfap97d1, Dnah17, Trll9, Pla2g3 and Vdac3 in mice." (PMID 38750428, 2024). "Studies using mouse models revealed that deletion of Ttll9, Vdac3, Dnah17, or Cfap97d1 resulted in the instability of sperm microtubule doublets 4–7, associated with sperm motility defects and male infertility." (PMID 34759295, 2021). "VDAC3 was also found to be essential for sperm motility; in the mice knockout of the VDAC3, the gene was associated with male infertility." (PMID 34421651, 2021). "Similarly, deletion of Vdac3, Pla2g3, and DNAH17 caused instability of sperm microtubule doublets 4–7, associated with sperm motility defects and male infertility." (PMID 32785227, 2020). "Thus, we suggest that arsenic-induced repression of VDAC3, PRKACA and GPD2 as well as the aberrant increase of L-tyrosine may disrupt the extent of protein tyrosine phosphorylation required for sperm capacitation, which then result in fertilization failure and male infertility." (PMID 27585557, 2016).
melanoma (5 papers, 2012 to 2022). A malignant, usually aggressive tumor composed of atypical, neoplastic melanocytes. "The broad-spectrum DUB inhibitor palladium pyrithione was also able to induce ferroptosis by promoting GPX4 protein degradation in lung cancer cells, while erastin promoted the UPS-dependent degradation of VDAC2 and VDAC3 during ferroptosis in melanoma cells." (PMID 36358651, 2022). "Here we identified VDAC2 and VDAC3 as two substrates of Nedd4 during erastin-induced ferroptosis in melanoma cells." (PMID 31974380, 2020). "In addition, E3 NEDD4 interacts with the PPxY motifs of VDAC2 and VDAC3 via its WW domain, thereby mediating K48-linked ubiquitination and degradation of VDAC2 and VDAC3 in melanoma cells." (PMID 36147464, 2022). "Furthermore, VDAC3 expression is upregulated in human malignant tumors, such as melanoma and thyroid tumors; VDAC3 is the binding site of the anticancer drug erastin, and overexpression of VDAC3 can increase sensitivity to erastin 8, 20-22." (PMID 35280682, 2022).
colon cancer (4 papers, 2019 to 2023). "This serves to explain the upregulation of mitochondrial PKM2 and VDAC3 in human colon cancer and to show how these molecules promote tumor development in vivo." (PMID 30787272, 2019). "We found there is a positive correlation of upregulation of mitochondrial PKM2 and upregulation of VDAC3 in human colon cancer." (PMID 30787272, 2019). "Otherwise, the protein expression levels of TRADD, H2AC6, VDAC3, JMJD7-PLA2G4B, TRAF2, and DAPK1 in colon cancer tissues and normal tissues in the HPA database were shown, which were consistent with the expression levels of these genes in RNA levels." (PMID 36505813, 2022). "Another study found that PKM2 desuccinylation during glucose deficiency prevented its translocation in the mitochondria and facilitated voltage dependent anion channel 3 (VDAC3) degradation by promoting mitochondrial pore opening, higher permeability, and inducing apoptosis in colon cancer cells." (PMID 36980194, 2023).
colorectal cancer (3 papers, 2019 to 2026). A primary or metastatic malignant neoplasm that affects the colon or rectum. "Increased levels of mitochondrial PKM2 and upregulated VDAC3 showed a significant positive correlation (R = 0.745, P = 0.035) in these colorectal carcinomas." (PMID 30787272, 2019).
acute lymphoblastic leukemia (2 papers, 2021 to 2025). Leukemia with an acute onset, characterized by the presence of lymphoblasts in the bone marrow and the peripheral blood. "In acute lymphoblastic leukemia, FBXW7 mediates VDAC3 ubiquitination, resulting in ferroptosis." (PMID 41268533, 2025).
breast carcinoma (2 papers, 2019 to 2024). "MCF-10A cells transfected with pmOGT-HaloTaq showed a significant decrease in VDAC1, VDAC2, and VDAC3 mRNA levels, whereas in MDA-MB-231 and Hs578t breast cancer cells only VDAC3 and VDAC1 mRNA levels decreased significantly after mOGT upregulation." (PMID 38473405, 2024).
Parkinson disease (2 papers, 2020 to 2025). A progressive degenerative disorder of the central nervous system characterized by loss of dopamine producing neurons in the substantia nigra and the presence of Lewy bodies in the substantia nigra and locus coeruleus. "Previous studies demonstrate VDAC3 involvement in Parkinson’s disease pathogenesis through its regulatory effects on mitochondrial dynamics and ROS biogenesis." (PMID 40901058, 2025).
asthenozoospermia (1 paper, 2024). "For example, Dnah17, Vdac3, and Pla2g3 loss induces destabilization of sperm MTDs 4–7, causing asthenozoospermia, whereas Ccdc176 KO mouse sperm exhibit axonemal structure deficiency in the absence of Dmt1 and/or 9 (missing Dmt1, Dmt9, or both)." (PMID 39516485, 2024).
brain ischemia (1 paper, 2018). Diminished or absent blood supply to the brain caused by obstruction (thrombosis or embolism) of an artery resulting in neurologic damage. "Our results showed that brain ischemia and reperfusion caused the downregulation VDAC1 and VDAC3, whereas VDAC2 was least affected after global ischemia." (PMID 30305621, 2018).
cardiac arrhythmia (1 paper, 2021). Any disturbances of the normal rhythmic beating of the heart or MYOCARDIAL CONTRACTION. "While VDAC3 did not mediate mitochondrial Ca2+ uptake in its wild-type form, replacing Q73 with a glutamate allows VDAC3 to facilitate SR-mitochondrial Ca2+ transfer, enhance mitochondrial Ca2+ uptake, and suppress cardiac arrhythmia." (PMID 34483974, 2021).
cervical cancer (1 paper, 2016). A primary or metastatic malignant neoplasm involving the cervix. "The expression of the other two members, VDAC2 and VDAC3, correlated with the metastasis of cervical cancer in the present study." (PMID 27419626, 2016). "To detect the expression of the candidate proteins in HPV16-positive cervical cancer tissues, we used IHC staining to assess the expression of VDAC1, VDAC2, VDAC3 and HPV16 E7." (PMID 27419626, 2016).
diabetes (1 paper, 2025). "In previous studies, VDAC3 has been implicated in various diseases such as cancer, diabetes, and neurological disorders." (PMID 38886317, 2025).
diabetic cardiomyopathy (1 paper, 2022). Diabetic cardiomyopathy is a disorder of the heart muscle in people with diabetes. "The pathways of neurodegeneration/multiple diseases and diabetic cardiomyopathy were also significant pathways and shared altered proteins such as Atp2a32, Uqcr10, Ndufa12, Vdac1, and Vdac3." (PMID 35565902, 2022).
endometrial cancer (1 paper, 2022). Primary or metastatic malignant neoplasm involving the endometrium (mucous membrane that lines the endometrial cavity). "However, high VDAC3 levels were expressed in poorly differentiated endometrial cancers and low VDAC3 levels in metastatic or advanced tumor stages." (PMID 36230654, 2022).
iron overload (1 paper, 2022). "Investigations of TF, FTL, PCBP1 and VDAC3 and their different specificities in terms of their roles in iron metabolism, independent of lipid-lowering treatment actions, may also be of high interest in the treatment of iron overload and deficiency." (PMID 35181730, 2022).
ischemia (1 paper, 2018). A hypoperfusion of the BLOOD through an organ or tissue caused by a PATHOLOGIC CONSTRICTION or obstruction of its BLOOD VESSELS, or an absence of BLOOD CIRCULATION. "Remarkable decreases in all three VDAC isoforms, especially VDAC1 and VDAC3, were observed in rat vulnerable hippocampal CA1 subfield after 15 min of global ischemia followed by reperfusion (I/R)." (PMID 30305621, 2018). "All three VDAC isoforms, especially VDAC1 and VDAC3, were downregulated in the susceptible hippocampal CA1 subfield, whereas no alteration occurred in ischemia-tolerant CA3/DG subfields, nor in postconditioning-treated brains." (PMID 30305621, 2018).
ischemic stroke (1 paper, 2018). A stroke disorder caused by obstruction of blood flow to the brain, due to thrombotic (local blood clot formation) or embolic (due to a blood clot or other material traveling from another site) event. "Moreover, si-VDAC2 and si-VDAC3 attenuated the postconditioning-induced neuroprotection, suggesting that stable presence of VDAC2 and VDAC3 also play important roles in neuronal survival after ischemic stroke." (PMID 30305621, 2018).
leukemia (1 paper, 2023). A malignant (clonal) hematologic disorder, involving hematopoietic stem cells and characterized by the presence of primitive or atypical myeloid or lymphoid cells in the bone marrow and the blood. "They revealed that autophagy-mediated upregulation of voltage-dependent anion channel 3 (VDAC3) promotes ferroptosis and that the activation of autophagy by rapamycin exerts synergistic anti-leukemia effects with erastin in vivo." (PMID 37190037, 2023).
neuroblastoma (1 paper, 2021). Neuroblastoma (NB) is the most common solid, extracranial childhood tumor. "Commercially available pharmacological inhibitors of SDHA (malonate), HSP90AB1 (geldanamycin), and VDAC3 (TRO19622) were used for functional evaluation of the TDP-43 genetic-interacting loci in N2a neuroblastoma cells." (PMID 33803845, 2021).
Sepsis (1 paper, 2025). Sepsis is defined as life-threatening organ dysfunction caused by a dysregulated host response to infection. "A previous study also confirmed that a decrease in VDAC3 in sepsis-induced myocardial injury and overexpression of VDAC3 reduce mitochondrial oxidative stress, reverse the progression of ferroptosis, and thus play a protective role in sepsis-induced myocardial injury." (PMID 40943454, 2025).
thyroid carcinomas (1 paper, 2021). "To explore the role of primary cilia in mitochondria-associated apoptosis in thyroid carcinomas, we examined expression of VDAC1, VDAC2, and VDAC3 mRNA in human PTC cells with or without ciliary loss." (PMID 33602982, 2021).
viral infections (1 paper, 2023). "Given recent findings that show over-oxidation of VDAC3 methionine and cysteine residues in both rat and human liver, it is possible that liver-associated pathologies in various disease states, including viral infections, are driven in part by VDAC3 PTMs." (PMID 37238738, 2023). "In the context of viral infections, hepatitis B virus (HBV)-encoded protein HBx has been shown to bind VDAC3 and alter the mitochondrial membrane potential, as well as activate STAT-3 and NF-κB." (PMID 37238738, 2023).
cancer (19 papers, 2015 to 2026). A tumor composed of atypical neoplastic, often pleomorphic cells that invade other tissues. "Other studies have reported that VDAC3-deficient cancer cells have reduced permeability for ADP/ATP and decreased mitochondrial membrane potential." (PMID 29854282, 2018). "VDAC3 has been linked to cancer and pathology as a potential marker of mitochondrial status." (PMID 36353119, 2022). "VDAC3 knockdown enhances autophagy and mitophagy, concomitantly reducing ROS and promoting cancer cell survival." (PMID 41617671, 2026). "Future studies are needed to understand clonal variability in CRISPR-Cas9 KO cell lines and the role of the VDAC3 isoform in cancer metabolism." (PMID 40568130, 2025). "On the contrast, in our study, suppressing expression of VDAC3 increased cancer cell’s sensitivity to CDDP." (PMID 37291676, 2023). "Voltage-dependent anion channels 3 (VDAC3) is upregulated in human malignant tumors, and overexpression of VDAC3 can increase sensitivity to erastin." (PMID 37291676, 2023). "Specifically, DFMO treatment upregulated the expression of MCU and VDAC3, indeed reversing the effects of cancer in the case of VDAC3." (PMID 36900391, 2023). "Subsequently, this translocation resulted in an increase in ATP generation and mitochondrial permeability through inhibiting voltage-dependent anion channel 3 (VDAC3) ubiquitination, promoting cancer cell survival." (PMID 33503959, 2021). "Evidence for a VDAC3 responsibility in specific mechanisms connected to cancer come from studies with erastin." (PMID 28066720, 2016). "Some reports in the literature show the involvement of VDAC3 in pathologies and diseases different from cancer." (PMID 28066720, 2016). "Erastin reprograms cancer cell metabolism by modulating VDAC2/VDAC3 and system xc- to trigger ferroptosis." (PMID 26405158, 2015). "Overall, these results allow us to speculate that the least expressed VDAC3 isoform is constitutively open in cancer cells for essential metabolite transport function." (PMID 40568130, 2025). "The isoforms of VDAC2 and VDAC3 are involved in erastin-mediated ferroptosis (cancer)." (PMID 38515787, 2024). "In most mammalian cells, including cancer cells, VDAC1 and 2 are the most abundant isoforms, whereas VDAC3 is the least expressed, except for testis and spermatozoa." (PMID 34658929, 2021). "However, in cancer cells, polyamine synthesis inhibition increased the expression of both MCU and VDAC3." (PMID 36900391, 2023). "Interestingly, VDAC3 expression seems not to be of prognostic value for human cancer suggesting isoform specific effects on cell proliferation." (PMID 34658929, 2021). "We observed upregulation of mitochondrial PKM2 in 6 of 8 tumor specimens and observed upregulation of VDAC3 in 5 of 8 cancer specimens as compared to adjacent nonneoplastic control tissues where neither of these molecules showed upregulation (c lane 4 vs. lane 3 for each patient)." (PMID 30787272, 2019). "It has also been reported that VDAC3 is the most important among the three VDAC isoforms to sustain ΔΨm in cancer cells, because the high levels of free tubulin inhibit VDAC1 and VDAC2, but not VDAC3." (PMID 28713289, 2017).